IL10 (interleukin 10)
Diseases named in the same sentence as IL10 in open-access papers (continued):
Sharing a sentence is not in itself a finding about the gene and the disease.
infection (continued). "Despite exhibiting comparable phenotypes, CD4+ YFP+ GFP+ T cells from the liver and lung produced significantly larger quantities of IL-10 than their splenic counterparts, showing that the CD4+ YFP+ GFP+ T cells exert graded functions in distinct tissue locations during infection." (PMID 26459508, 2016). "H56-specific IL-10 was seen in all groups independent of their Th-profile and was not augmented by the infection." (PMID 26791076, 2016). "TNFα and IL-10 concentrations were slightly higher following infection with 6B rather than 7F but not significantly, although significantly higher than the non-encapsulated mutant." (PMID 27009189, 2016). "As expected, no spike in IL-10 expression was seen in the kidneys of both groups of mice after infection." (PMID 26907352, 2016). "We also identified differences between the responses of young and aged mice to infection, including four markers that were significantly elevated in young mice (IL-1β, IL-10, IL-13, eotaxin) but not aged or dam mice." (PMID 27936166, 2016). "Thus, it is notable that anti-ICOS administration from day 3 of infection, after initial CD4+ T cell priming and differentiation events, led to impaired IL-10 production by parasite-specific CD4+ YFP+ T cells." (PMID 26459508, 2016). "Whereas the secretion of IL-6 by spleen cells was unaffected by the lack of IL-22, the splenic production of IFN-γ, TNF and IL-10 was increased in IL-22−/− mice compared to wild-type mice at day 14 post infection." (PMID 27650379, 2016). "In order to test this hypothesis, WT mice infected with T. gondii, treated or not with a single dose of DTA-1 were sacrificed 5 days after infection and had their lungs homogenized and analyzed for IFN-γ and IL-10 production." (PMID 27027302, 2016). "It was observed that the anti-inflammatory cytokine IL-10 serum level was significantly higher in patients with SAI than in patients without an infection (P = 0.000)." (PMID 27453748, 2016). "Infections with P. falciparum detected at inclusion were associated with enhanced non-specific TNF responses, whilst diminished non-specific and DBL-5-specific IL-10 responses were associated with infections detected at delivery." (PMID 27653505, 2016). "Since MCs and serglycin proteoglycans may contribute to the pro-inflammatory cytokine signaling during infection, we analyzed the serum levels of the pro-inflammatory cytokines TNF-α and IL-1β, and the regulatory cytokine IL-10." (PMID 27267469, 2016). "The overall ratio of IL-10 to IFN-γ secretion by CD8+ T cells was significantly reduced in PD-1KO mice compared to WT mice, consistent with better pro-inflammatory CD8+ T cell responses to re-infection." (PMID 27217330, 2016). "While our studies have demonstrated that IL-10 is not solely responsible for dampening the immune response to permit infection to occur, it does play a role in modulating the immune response to S. epidermidis infection in the CNS." (PMID 27737696, 2016). "Interleukin- (IL-) 4- and IL-10-producing CD4+and CD8+ T-cells were present in both La and Lb infection; however, interferon- (IFN-) γ-producing CD4+and CD8+ T-cells were detected only in Lb infection." (PMID 27073297, 2016). "This indicates that in utero priming determines the Treg and IL-10 production independent of acquisition of infection in later life." (PMID 27861499, 2016). "Indeed, production of the anti-inflammatory cytokine IL-10 by CD11c+ cDC following FMDV A24 Cruzeiro occurred 1 day earlier than O1 Manisa, and was sustained for several days post-infection." (PMID 27008425, 2016). "We found that macrophages from gp91phox−/− and WT mice produced similar levels of IL-6, TNF-α, IL-17A and CXCL-1, MCP-1 and IL-10, regardless of infection with L. amazonensis." (PMID 27056545, 2016). "This infection-dependent increase was essentially abolished in all cases by probiotic therapy (experimental group 2) (p = 0.006 for TNF-α; p = 0.0003 for IL-6; p = 0.047 for IL-10)." (PMID 27780258, 2016).
infection (continued). "Therefore, we calculated the average IL-10: TNF-α ratio for a healing response, a hyperinflammatory response, and organ dysfunction during infection in 10 simulation runs." (PMID 27556404, 2016). "In mice, infection with K. pneumoniae promoted MDSC expansion and thus increased levels of IL-10." (PMID 27066459, 2016). "The dynamics of IL-10, TGF-β and IFN-γ gene expression in the ileum, ileocecal junction, ileocecal lymph node, and mesenteric lymph nodes of healthy cows as well as those in subclinical and clinical stages of infection." (PMID 27905994, 2016). "In support of this hypothesis, blockade of ICOS from day 3 of infection, which is after CD4+ T cell priming, significantly abrogated the expression of IL-10 by parasite-specific CD4+ T cells in all examined organs." (PMID 26459508, 2016). "In IL-10 KO mice, we noted no change in bacterial burdens, showing that IL-10 is not needed to control the infection in a CNS catheter infection model." (PMID 27737696, 2016). "Similarly, genetic and Ab-mediated blockade of IL-10 signaling decreases the mortality rate and brain virus load in murine West Nile Virus (WNV)-infection." (PMID 27611574, 2016). "We detected IL-10 and TNF-α in mouse sera 10 h after Absettarov-strain infection." (PMID 28163697, 2016). "In spleen, both IL-12 and IL-10 cytokines were elevated after infection with replicating strains, in contrast to non-replicating cps1-1 strain that did not induce this change." (PMID 27721814, 2016). "Regardless of the type of infection, IL-10 limits Th1 and Th2 effector responses by suppressing function of macrophages and DCs." (PMID 27882241, 2016). "Additionally, mRNA levels of Gal-9, Tim-3, CD44, CD137, and PDI were significantly increased in the lungs at day 5 after infection, and the levels of CD137, IFN-α, IFN-β, IFN-γ, IL-4, and IL-10 in the lungs were also increased after α-lactose treatment." (PMID 27554340, 2016). "After 60 h of infection, at the more acute phase, the bacteria had induced a substantial increase in the expression of genes for most proinflammatory cytokines, including IFN-γ, IL-1β, IL-2, IL-6, IL-8, IL-22, and TNF-α, as well as genes for IL-10 and IL-4." (PMID 27357336, 2016). "Further in their study the authors also observed increased IFN-γ/IL-10 ratio after 5 months of infection in non-immunized animals which does not explain the role of increased IFN-γ levels in protection." (PMID 26752686, 2016). "Unexpectedly, all 4 IL-10−/− knockout K562 strains sustained DENV-ADE infection without decreased enhancing activity compared with that found in wild type K562." (PMID 26923481, 2016). "Even so, IL-6, IL-10, and IFN-β levels were all increased immediately after infection at 1 d.p.i.." (PMID 27252695, 2016). "Upon infection with L. monocytogenes increases and decreases in gene expression were observed which were enriched for TREM1, IL-10 and Granulocyte Adhesion and diapedesis some of which are in keeping with previously reported mechanisms of protection or pathogenesis." (PMID 26918359, 2016). "Notably, IL-10 exerted quantitatively stronger regulatory effects on innate and CD4+ T cell responses during primary and secondary infections, respectively." (PMID 27630165, 2016). "Due to infection of macrophages with AG83+Sias, reduction of the genetic expression of Th1 cytokine genes (IFNγ and IL-2) and upregulation of Th2 cytokine genes (IL-4, IL-10 and TGFβ) were observed." (PMID 27494323, 2016). "Recent studies demonstrated that γδ T cells exhibit Th1-, Th2-, Th17-, and Treg-like features and can produce corresponding cytokines, such as the inflammatory cytokines IFN-γ and TNF-α and the anti-inflammatory cytokines IL-10, TGF-β, and IL-17, in various infection and autoimmunity models." (PMID 26981547, 2016). "This activity decreased similarly between groups, until day 7 post-infection, from which time on there was a non-significant trend for surviving IL-10−/− animals to move less." (PMID 27557867, 2016).
infection (continued). "Mir155 primary transcripts were also elevated in joints of Il10-/- (but not B6) mice at 4 weeks post-infection." (PMID 26252010, 2015). "In the group immunized with empty vector we detected higher ratios of IFN-γ /IL-10 and IFN-γ/TGF-β two months after infection, suggesting that the infection could be responsible for this increase." (PMID 25642946, 2015). "IL-10 mRNA expression appears to show a Th2-type response in naive infection but not protective immunity." (PMID 25410206, 2015). "It has been previously demonstrated that IL-10 inhibits accumulation and activation of M1-type myeloid cells, in particular, TIP-DCs (CD11b+Ly6C+CD11c+TNF and iNOS producing DCs) in the liver during infection with African trypanosomes." (PMID 26222157, 2015). "Similar patterns were observed in infection with low-risk HPV, although the trend of not healing was more modest, revealing a significant difference only for IL-10." (PMID 25663851, 2015). "The activation of this network after clearance may indicate a homeostatic mechanism in infection-experienced cells and it is concordant with the regulatory function of IFN-β1 in inhibiting the IFN- γ pathway through the induction of IL-10." (PMID 26214306, 2015). "After treatment, when the infection had been controlled, the expression of TLR2 and TLR4 was still detected, and these TLRs may have been involved in the production of TNF-α, IFN-γ, IL-10 and NO, while TLR4 was involved in the production of IL-17." (PMID 25706930, 2015). "No significant increase in IL-10 secretion was observed during the early phase of infection with T. canis (data not shown)." (PMID 26135397, 2015). "The percentage of monocytes expressing IL-10 was higher after the infection by the two strains in infected and non-infected monocytes." (PMID 26147698, 2015). "Other lymphocytes, which are absent in Rag2-/- skin, such as B cells and CD8+ T cells were rare in infected skin (<1000 cells) and did not expand in number, or proportion after repeated infection, nor did they produce IL-10." (PMID 25974019, 2015). "Exacerbated infection by L. major required lipid bodies/PGE2 and IL-10 by B-1CDP cells." (PMID 25933287, 2015). "The infection with either strain did not alter the percentage of expression of IL-10 by CD4+ T lymphocytes." (PMID 26147698, 2015). "IL-10 expression is induced by PCV2, but not by non-pathogenic PCV1, infection in vitro cultured PBMCs, especially the monocyte/DC/macrophage populations." (PMID 28405423, 2015). "Significant amounts of IL-10 were also observed in naïve mice immunized with rSm22.6 plus Alum or without adjuvant, which also did not confer protection to challenge infection." (PMID 25723525, 2015). "Between days 23 and 27 post infection clinical signs were noted in both IL-10 treated and non-treated infected animals." (PMID 26505761, 2015). "Moreover, the genetic ablation of IL-10 prevents the detrimental effect of Lutzomyia longipalpis SGE on both Leishmania major and L. amazonensis infections." (PMID 25849562, 2015). "The IL-10 production as observed in infection-free children (group G0) did not further enhance with double (G2) or poly-parasite (G3+) infections, however, it diminished post anti-parasite treatment." (PMID 25698903, 2015). "Reduced levels of IL-10 also allow amplification of pro-inflammatory Th1 cytokine cascade, which leads to brain damage, as shown in post-mortem studies and in experimental models of neuro-arbovirosis, including WNV, JEV and TBE infections." (PMID 26569288, 2015). "B-1CDP cells produce a large quantity of IL-10 even without stimulation, in agreement with a marked anti-inflammatory profile, and with a propensity for infection by Leishmania." (PMID 25933287, 2015). "Infection also failed to stimulate the production of IL-10 by Foxp3+ Treg cells, despite increased IL-10 production by CD4+ Foxp3− IL-4+ Th2 cells." (PMID 26195548, 2015).
infection (continued). "Although IL-10 induces CD200R expression by macrophages in vitro, MCMV-infected IL-10-/- mice exhibited no alterations in CD200R expression by myeloid cells during infection." (PMID 25654642, 2015). "P. vivax infection reduces the numbers of different subsets of CD8+ T cells, particularly the memory cells, during blood-stage of infection and enhances the number of CD8+ memory T cells expressing IL-10, which positively correlates with the number of cells expressing TNF-α and IFN-γ." (PMID 25636730, 2015). "A careful dissection of the transcription profile by day 1 pi in tissues from E75CV1-infected pigs, allowed the confirmation of the significant up-regulation of CD163, IL-1β, IFN-γ, IL-5, IL-6, IL-10, IL-12p40, TNF-α and TGF-βR1 and the down-regulation of DEFB2, immediately after E75CV1 infection." (PMID 26589145, 2015). "Interestingly, infection with N. gonorrhoeae significantly induced pro (IL-6 and TNF-α) and anti-inflammatory (IL-10) cytokines in M0-MФ." (PMID 26125939, 2015). "Treatment with PZQ, ARA, or PZQ combined with ARA led to a highly significant (P < 0.0001) decrease of 42–54% in IL-10 levels, again regardless of baseline infection intensity." (PMID 25624403, 2015). "The concentrations of all cytokines and chemokines in the spleen 20 hours after infection (IL-6, IL-10, CXCL1, and CXCL2) were not different among all three groups studied." (PMID 25563481, 2015). "IL-10 and TGF-â expression increased in the thymus with either Harbin-1 or Ts strain infection." (PMID 25803101, 2015). "The lower value of the IL-10/ IFN-γ ratio observed in the LiPABP vaccinated and protected mice after infection indicates that the Th1 response induced by vaccination with the genetic combined vaccine against the three member of the LiPABP family was maintained after infection." (PMID 25955652, 2015). "With increased time of infection, the expression of M1 macrophage-related markers, including CD86, CXCL11, and TNF-α decreased, while the expression of M2 macrophage-related markers including CD206, CCL17 and IL-10 gradually increased." (PMID 26091535, 2015). "H1N1pdm09 infection alone did not induce an IL-10 response from either pregnant or non-pregnant PBMCs when compared to media (75 pg/mL, 95 CI 34–114 pg/mL)." (PMID 25831059, 2015). "The serum concentration of IFNγ, TNFα, IL-10 and IL-6 only started to increase substantially on day 6 post-infection, and no apparent difference was observed in the serum levels of IL-1β." (PMID 25768944, 2015). "Furthermore, in this same experiment, we also examined the production of IL-10 and IL-17, since IL-10 restrains IL-17-induced lung pathology following pulmonary Ft-LVS infection." (PMID 25961064, 2015). "In contrast, DCs from Hif1aflox/flox—Cd11c-Cre+ mice failed to upregulate IL-10 expression during the first week of infection." (PMID 26046638, 2015). "Irrespective of the C. jejuni strain, however, gnotobiotic IL-10−/− mice get readily colonized by the pathogen at high loads following peroral infection." (PMID 24959425, 2014). "Interestingly, blocking of TLR4 before infection decreased epithelial IL-6 secretion, but increased the CREB-activated IL-10 production." (PMID 24489729, 2014). "In E. multilocularis lesions, IL-10 mRNA expression was also biphasic, with a significant increase at the early and late stages of infection, but not at its middle stage." (PMID 24637903, 2014). "The ratio of IFN-γ/IL-10 response in the CHR and HI groups is related to the immunoregulatory effect as a mixed Th1/Th2 profile since these individuals have no impairment of lymphocytes and IFN-γ, which is a key cytokine for the control of infection." (PMID 25352834, 2014). "Similar numbers of intracellular bacteria were found between the WT and flaA mutant 4 hours post-infection, indicating low IL-10 expression in response to the flaA mutant was not due to defective phagocytosis." (PMID 24823621, 2014).
infection (continued). "The comparison of cytokine gene expression profiles between T cell lines in acutely and persistently infected deer mice revealed an increase of TGF-β and FoxP3 mRNA expression and a decrease of IL-10 and IL-4 expression during the persistent phase of SNV infection in most of the lines studied." (PMID 24859344, 2014). "Infection of burn mice resulted in a substantial elevation of serum IL-10 while infection of sham mice did not induce an IL-10 response." (PMID 24454904, 2014). "Infection also increased the levels of the immunoregulatory cytokine IL-10 in serum and BAL of WNC mice; however, MNC mice were not able to increase the production of this cytokine in response to pathogen." (PMID 24691464, 2014). "Here, cytokine and chemokine production during HSV-2 infection showed size-related differences for each nanoparticle type - presence of 13 nm AgNPs at the time of infection led to production of CCL2, IFN-γ and IL-10, while 33 nm AgNPs induced CCL2, TNF-α and IL-10." (PMID 25117537, 2014). "We observed a significant 2.5-fold increase in the IL10 transcript in sorted splenic CD4 T cells at day 250 after infection (P<0.05), with no changes in the expression of TGFB1." (PMID 24763747, 2014). "For the MP287/03 Mbv infection, comparable low levels of IL-1β were found in cell supernatants from C57BL/6 and P2X7R−/− mice, but the lack of P2X7R resulted in an increase of IFNγ and a decrease of IL-10." (PMID 24991816, 2014). "In contrast, infection of BALB/c mice with L. major causes a non-healing Th2 form of the disease, characterized by expression of the cytokines IL-4, IL-13, and IL-10." (PMID 25255101, 2014). "It is possible that in vitro infection of DC by MCMV also affects their expression of cytokines, to prevent the delivery of an activating signal 3 to antiviral CD8 T cells or even to induce the release of an inhibitory signal 3 such as IL-10." (PMID 25120535, 2014). "We observed that IFN-γ, TNF-α, IL-6 but not IL-10 production was increased initially 18 hours post-infection and decreased gradually thereafter following treatments with AMP and AZM." (PMID 24565171, 2014). "It is also entirely possible that the balance of regulatory cytokines such as IL-10 and TGF-β may change with host genetics, infection level, and stage of parasite life cycle and, therefore, in function." (PMID 24942690, 2014). "This revealed that IL-10 was readily detected after Nb infection, but after STm infection the levels were similar to those of non-infected cultures." (PMID 25474738, 2014). "More recently the expression of IL-10 has been shown in the cecal tonsils in birds infected with S. Enteritidis at 4 days post-infection but not following infection the non-inflammatory avian-adapted serovars." (PMID 25346731, 2014). "The elevated IL-10-producing B cells in gut tissue from HIV-1 infected individuals reported here is interesting since gut is one of the main sites of HIV-1 replication and immune destruction early in the infection." (PMID 24586620, 2014). "The immune responses observed in the convalescent model would not have time to develop in a standard intranasal infection, although it would be of interest to see if IL-10−/− mice phenocopy XID mice in the convalescent model of Schu S4 infection." (PMID 24639953, 2014). "For the inflammatory response, nicotine could suppress the secretion of IL-1α, IL-4, IL-5, IL-10 and RANTES on day 6 and IL-17 on day 14 significantly after H9N2 infection compared with control mice." (PMID 24465940, 2014). "Their conclusion that the IL-10-expressing APCs were not infected was based upon infectious center assays, which determine the level of productive infection, but cannot identify the level of abortive infection." (PMID 24613988, 2014). "Regarding the early detection of IL-10 at 24 h post-infection, the factors which show crosstalk with CREB are speculated to be important for regulating IL-10 expression." (PMID 25412261, 2014).